NAMPT (nicotinamide phosphoribosyltransferase)
Diseases named in the same sentence as NAMPT in open-access papers (continued):
Sharing a sentence is not in itself a finding about the gene and the disease.
glioma (continued). "Several studies have shown that the ability of NAMPT to generate NAD+ is important in promoting glioma, and other cancers, by increasing the activity of NAD+-dependent enzymes." (PMID 37037593, 2023). "We then examined MVs derived from the glioma cell line U-87 MG, which expresses very high levels of NAMPT and is able to proliferate when subjected to radiation similar to GSC-267 cells." (PMID 37037593, 2023). "Studies have reported that NAMPT overexpression led to increased glioma stemness and glioblastoma multiforme patients with higher levels of NAMPT expression had poor prognosis than those with lower expression." (PMID 37689115, 2023). "We found that IDH1R132H leads to the upregulation of NAMPT expression on mRNA level in our glioma cell model, in line with NAD+ synthesis upregulation in those cells." (PMID 35628596, 2022). "Previous analysis of key enzymes of those pathways identified NAMPT as the only one expressed in all investigated glioma cell lines and patient-derived glioma cell models." (PMID 35628596, 2022). "The essential role of NAMPT in maintaining NAD+ levels has led to NAMPT inhibitors that can trigger apoptosis in glioma stem-like cells." (PMID 35806160, 2022). "Another long-stranded non-coding RNA, gastric cancer-associated transcript 3 (GACAT3), promotes the development of gliomas by functioning as a molecular sponge for miR-135a, blocking its interaction with NAMPT, and controlling NAMPT production." (PMID 36160449, 2022). "Of the various NAD+ synthesis enzymes, we found NAMPT to be the only one ubiquitously expressed among different patient-derived glioma cell lines, making it a natural target in those cells." (PMID 35628596, 2022). "NAMPT overexpression has been observed in multiple malignant tumors, including breast, ovarian, thyroid, gastric, prostate and colorectal cancers, gliomas, and malignant lymphomas." (PMID 33912035, 2021). "Given that IDH1-mutant cancers are exquisitely reliant on NAMPT for their NAD supplies (as they downregulate NAPRT expression), NAMPT inhibitors were found to exhibit remarkable antitumor activity against IDH1-mutant glioma and fibrosarcoma xenografts." (PMID 34068917, 2021). "The overexpression of NAMPT cDNA in glioma or colorectal cells increased their tumorigenic properties, as well as their acquisition of the CSC phenotype and properties in culture." (PMID 33384409, 2021). "NAMPT is overexpressed in high-grade glioma and GBM tumors, and its levels correlate with tumor grade and prognosis." (PMID 32028963, 2020). "A connection between NAMPT activity and invasive/stemness properties was recently reported in leukemia, glioma, colon and breast cancers." (PMID 33419372, 2020). "This renders the IDH mutant glioma vulnerable to inhibition through the nicotinamide phosphoribosyltransferase (NAMPT) catalyzed NAD+ salvage pathway." (PMID 32825279, 2020). "Ectopic overexpression of NAMPT in glioma cell lines is associated with the enrichment of glioblastoma CSC population and inhibition of NAMPT blocks in vivo tumorigenicity of glioblastoma CSCs." (PMID 32028963, 2020). "Although our results indicate that NAMPT is the most important enzyme for NAD-biosynthesis in gliomas, we found its expression to be lower in IDH-mutant gliomas compared to glioblastomas." (PMID 31888244, 2019). "IDH1-mutant glioma required NAMPT for the production of NAD+ and showed vulnerability to the inhibition of NAMPT, because mutant IDH1 reduces the expression of NAPRTase22." (PMID 31123329, 2019). "The Cancer Genome Atlas (TCGA) data analysis confirmed lower NAMPT expression in IDH1-mutant versus IDH1-wildtype gliomas." (PMID 31888244, 2019). "Ectopic overexpression of NAMPT in Glioma cell lines increases tumorigenic properties controlling stem cell pathways and enriching the GSCs population." (PMID 31119097, 2019).
glioma (continued). "The use of NAMPT inhibitors (synthetic lethality) caused a severe metabolic crisis inducing the activation of AMPK, and autophagy-mediated cell death in glioma cells and in mice harboring intracranial IDH mutant glioma xenografts." (PMID 29439493, 2018). "FK866, a NAMPT inhibitor, was tested as a possible therapy for gliomas in mass cultures and tumorspheres representing CIC populations." (PMID 29245920, 2017). "In this work, we systematically explored the role of NAMPT in gliomas and demonstrated that NAMPT is a strong oncogene that induces essential developmental and stem cell pathways, facilitating the dedifferentiation of tumor cells into CICs." (PMID 29245920, 2017). "Meta-analysis reveals that NAMPT is also a key factor inducing cancer stem pathways in glioma cells." (PMID 29245920, 2017). "Our data are in accordance with those of most previous works indicating that stem cell pathways upregulation has greater tumorigenic potential in human cancer and that a positive correlation exists between glioma stage and NAMPT expression." (PMID 29245920, 2017). "Ectopic overexpression of NAMPT in glioma cells increases its protumorigenic properties, as well as its cancer initiating cell-like physiological properties." (PMID 29245920, 2017). "We report that NAMPT overexpression in glioma cell lines increases tumorigenic properties controlling stem cell pathways and enriching the cancer-initiating cell (CIC) population." (PMID 29245920, 2017). "With the aim of identifying the pathways that induce cell stemness and pluripotency, we correlated NAMPT expression with stem cell pathways in several in silico glioma retrospective studies (GSE16011, GSE4290, GSE4271, GSE43378, and GSE7696)." (PMID 29245920, 2017). "Ourresults suggested that the correlation between NAMPT expression andglioma grading aligned with previous studies and supported the idea that NAMPT may play a role in glioma aggressivenessand progression." (PMID 38924492, 2024). "Recent findings indicate that the transfer of nicotinamide phosphoribosyltransferase (NAMPT) through microvesicles from radio-resistant glioma stem cells can enhance intracellular NAD+ levels in recipient cells, thereby promoting their resistance to radiation therapy." (PMID 39594811, 2024). "Glioma arising from different cellular backgrounds may respond differently to NAMPT inhibition according to varying metabolic properties, such as variations in the expression of NAD+ synthesis enzymes." (PMID 35628596, 2022). "Moreover, GACAT3 also mediates glioma cell proliferation by regulating NAMPT via competitive binding to miR-135a." (PMID 35127682, 2022). "Glioma cells overexpressing NAMPT were shown to be more sensitive to its inhibition." (PMID 35628596, 2022). "Similarly, in gliomas, gastric cancer-associated transcript 3 (GACAT3), another long non-coding RNA, regulates NAMPT expression and promotes glioma progression by acting as a molecular sponge to miR-135a, inhibiting its interaction with its target, NAMPT." (PMID 34068917, 2021). "NAMPT is also a key factor inducing cancer stem-like pathways in glioma cells." (PMID 31119097, 2019). "Targeting GSCs depicts a new frontier in Glioma therapy; hence NAMPT could represent a key regulator for GSCs maintenance." (PMID 31119097, 2019). "In this study, we investigate the oncogenic role of PPM1D, a protein phosphatase often found truncated in pediatric gliomas such as DIPG, and uncover a synthetic lethal interaction between PPM1D mutations and nicotinamide phosphoribosyltransferase (NAMPT) inhibition." (PMID 31439867, 2019). "NAMPT is overexpressed in a broad range of solid tumors including colorectal, ovarian, breast, gastric, prostate, well-differentiated thyroid cancers, melanoma, gliomas, and endometrial carcinomas." (PMID 31119097, 2019).
glioma (continued). "We found that glioma tumorspheres are sensitive to NAMPT inhibitors, particularly tumorspheres with high levels of NAMPT expression, which indicates that NAMPT inhibition may be a suitable therapy for glioblastoma." (PMID 29245920, 2017). "Furthermore, we showed that NAMPT represents a promising target for future glioma treatments focused on the CIC subpopulation." (PMID 29245920, 2017). "Altogether, these data demonstrate that NAMPT expression in gliomas is an independent indicator of poor patient outcomes, which may indicate that NAMPT has an important oncogenic function in glioma cells -." (PMID 29245920, 2017). "Therefore, their identification may provide the key to treating glioma cases where NAMPT is overexpressed." (PMID 37037593, 2023). "New efforts in therapeutic methods, such as the targeted delivery of siRNA or the use of extracellular vesicles as drug delivery systems, may allow us to selectively reduce NAMPT expression in IDH1R132H glioma and might be worth investigating in future studies." (PMID 35628596, 2022). "Importantly, NAMPT was ubiquitously expressed in all the patient-derived glioma cell models." (PMID 31888244, 2019). "Therefore, NAMPT represents a novel therapeutic target in Glioma progression and relapse." (PMID 29245920, 2017). "Secreted signals in MAN1C1-expressing glioma cells, such as PTN, MIF, ANXA1, MDK, and NAMPT, allowed MAN1C1 to interact with myeloid/microglial cells." (PMID 39333557, 2024). "Consistent with the changes in expression, patients with higher expression of LDHA, MIF, NAMPT, PGK1, SAT1, and PLOD2, and lower expression of ALDOC, ABAT, ADCY2, GALNT13, and PDE8B showed poorer survival rates in all glioma samples." (PMID 38989284, 2024). "Similar to the TCGA datasets, all 11 genes exhibited WHO grade-dependent expression in glioma samples, with 6 upregulated (LDHA, MIF, NAMPT, PGK1, SAT1, and PLOD2) and 5 downregulated genes (ALDOC, ABAT, ADCY2, GALNT13, and PDE8B)." (PMID 38989284, 2024). "In our study NAMPT, NMNAT1 and NMNAT3 were found significantly upregulated in glioma samples compared to the controls." (PMID 36809279, 2023). "We characterize in detail one such mechanism that involves the transfer of the metabolic enzyme nicotinamide phosphoribosyltransferase (NAMPT) to radiosensitive cells, mediated by MVs shed by radioresistant GSCs and glioma cells (NAMPT-high MVs)." (PMID 37037593, 2023). "The transfer of the metabolic enzyme NAMPT via microvesicles and the accompanying elevated levels of NAD are found to be a mechanism by which glioma cells become resistant to radiation." (PMID 37037593, 2023). "In glioma, GACAT3 substantially upregulates NAMPT expression, which enhances cell migration and invasion via sponging miR-135a in U87 and U251 cells." (PMID 35127682, 2022). "We previously analyzed the expression levels of the rate-limiting enzymes of the four NAD+ synthesis pathways in glioma cells and astrocytes and found the two salvage pathways via NMRK1 and NAMPT to be the sole contributors to NAD+ synthesis." (PMID 35628596, 2022). "In this work, we explored the effects of IDH1R132H on NAD+ metabolism and the therapeutic potential of NAMPT knockdown and NAMPT small-molecule inhibitors in IDH1wt and IDH1R132H glioma cells." (PMID 35628596, 2022). "Nicotinamide phosphoribosyltransferase (NAMPT) is the main enzyme for NAD+ biosynthesis and has been found to be upregulated in several cancers including glioma." (PMID 34685601, 2021). "Other therapeutic strategies exploiting potential metabolic vulnerabilities in IDH1mut gliomas, including inhibitors of poly (ADP-ribose) polymerase and nicotinamide phosphoribosyltransferase, are also being pursued." (PMID 34424450, 2021). "For instance, glioma cells were found to express QAPRT and utilize QA as a NAD precursor to protect themselves from oxidative stress and NAMPT inhibition, thereby drawing attention to the de novo NAD synthesis pathway as a potential therapeutic target." (PMID 34068917, 2021).
glioma (continued). "Notably, PPM1D mutant cells are shown to be sensitive to NAMPT inhibitors in vitro and in vivo, within both engineered isogenic astrocytes and primary patient-derived model systems, suggesting the possible application of NAMPT inhibitors for the treatment of pediatric gliomas." (PMID 31439867, 2019). "That cellular NAD(H) is more sensitive to NAMPT inhibition by FK866 was also observed for the Maf-DKO cell line and for U251 glioma cells and activated T cells in previous studies." (PMID 24824795, 2014). "mIDH1 gliomas downregulate NAPRT1, rendering cells dependent on the NAD+ salvage enzyme NAMPT." (PMID 40931345, 2025). "Therefore, future studies are required to validate our findings regarding pharmacological NAMPT inhibition, ideally in patient-derived IDH mutant glioma models." (PMID 35628596, 2022). "IDH1-mut glioma cells lowered NAD+ levels by silencing the NAD+ salvage enzyme nicotinic acid phosphoribosyltransferase (NAPRT) and are sensitive to the block of NAD+ biosynthesis via nicotinamide phosphoribosyltransferase (NAMPT) inhibition." (PMID 35267433, 2022). "We previously identified NAMPT as the only NAD+ synthesis enzyme that is ubiquitously expressed in IDH mutant and IDH wild-type gliomas and that NAMPT protein expression is lower in IDH mutant gliomas." (PMID 35628596, 2022). "The decrease in metabolic activity we found after treatment with these agents complies with our data after esiRNA-mediated NAMPT inhibition, as well as reports of decreased levels of NAD+, NADH, NADP+ and NADPH in glioma cells with and without IDH1 mutation." (PMID 35628596, 2022). "In keeping with this notion, mutations in the protein phosphatase Mg2+/Mn2+-dependent 1D (PPM1D) gene in pediatric gliomas also drive NAPRT gene silencing through the hypermethylation of CpG islands in the NAPRT promoter, thus, again conferring unique sensitivity to NAMPT inhibitors." (PMID 34068917, 2021). "Unlike glioma cells, NAMPT inhibitors will ultimately target cells in an active cell cycle under replicative stress, two main hallmarks of GSCs." (PMID 31119097, 2019). "Moreover, NAMPT was the only protein also expressed in each of eight patient-derived IDH-mutant and -wildtype glioma cell models; six of them also showing measureable NMRK1 expression." (PMID 31888244, 2019). "NAMPT is crucial for replenishment of the intracellular NAD pool, and in several cancer types - including prostate, gastric, breast, and ovarian cancer, gliomas, leukemia, lymphoma, and myeloma - NAMPT was found to be overexpressed and associated with disease progression." (PMID 28160567, 2017). "Altogether, our results indicate that targeting the NAD+ synthesis pathway is a promising therapeutic strategy in IDH mutant gliomas; however, the agent should be carefully considered since three small-molecule inhibitors of NAMPT tested in this study were not suitable for this purpose." (PMID 35628596, 2022). "Additionally, IDH1, R132H, and PPM1D mutant gliomas have been shown to selectively rely on NAD salvage pathways, suggesting these sub-populations of tumors may benefit from NAMPT inhibition." (PMID 35814452, 2022). "Nicotinamide phosphoribosyltransferase (NAMPT), in our experiments more than 4-fold upregulated after ESR2 knockdown in HEC-1A cells, is overexpressed in several cancer entities such as ovarian, breast, gastric, colorectal, and prostate cancer, gliomas and B-cell lymphomas." (PMID 31357971, 2019). "Indeed, we found, overall, higher levels of NAD+-synthesis enzymes NAMPT, NMRK1, and QPRT as well as NADK in primary glioblastomas compared to low-grade gliomas and astrocytes in our and publicly available data, indicating an overall increase in NAD+-biosynthesis in malignant cells." (PMID 31888244, 2019).
glioma (continued). "Therefore, NAMPT overexpression facilitates self-renewal cell properties, resulting in stemness-like maintenance, which ultimately leads to increased migration, de-differentiation and CIC-dependent resistance to therapy, which are features of glioma tumors." (PMID 29245920, 2017). "Thus, we believe that NAMPT inhibitors, in combination with TMZ may represent a new therapy for glioma CIC populations, particularly in patients expressing high levels of the gene signature." (PMID 29245920, 2017).
glioblastoma (37 papers, 2011 to 2026). The most malignant astrocytic tumor (WHO grade IV). "Similarly to what we observed in vitro, the PDX with the IDH1R132H mutation had lower protein levels of NAMPT compared to the IDH1-wildtype glioblastoma." (PMID 31888244, 2019). "We first compared NAMPT expression in differentcell lines to demonstrate its overexpression in glioblastoma." (PMID 38924492, 2024). "NAMPT is not only highly expressed in glioblastoma celllines but also associated in clinics with a worse prognosis for braincancer patients: a high NAMPT protein level is associated with a highergrade of GBM." (PMID 38924492, 2024). "It was reported that NAMPT inhibitor FK866 induced cell death in C6 glioblastoma and IDH1 mutant gliomas by depleting NAD." (PMID 39336077, 2024). "These insights not only reinforce the potential of NAMPT inhibitors like FK866 in glioblastoma treatment but also introduce F-NR as a promising adjunct to enhance therapeutic efficacy." (PMID 39336077, 2024). "Another OGT target gene with a significant role in glioblastoma tumorigenesis is nicotinamide phosphoribosyltransferase (NAMPT), which is a rate-limiting enzyme of the salvage pathway to regenerate adenine dinucleotide (NAD)." (PMID 37689115, 2023). "By causing metabolic stress, inhibition of NAMPT offers a novel therapeutic approach in tumors that lack NAPRT expressions, such as glioblastoma and lymphoma." (PMID 36845744, 2023). "IDH1/2 mutant tumors such as glioblastomas, chondrosarcomas, and gastric cancers have also been shown to be more sensitive to NAMPT inhibition." (PMID 35814452, 2022). "Through the transcription factor C/EBP-β, mesenchymal glioblastoma stem cells selectively increase the expression of NAMPT and NNMT and interact with their gene regulatory areas." (PMID 36160449, 2022). "High levels of NAPRT and NAMPT have been found in ovarian, prostate and pancreatic cancers, while in glioblastoma, neuroblastoma, chondrosarcoma, leukaemia and gastric and colon cancers, low levels of NAMPT and low levels of NAPRT have been found." (PMID 36078035, 2022). "In glioblastoma-bearing mice, the local delivery of microparticles loaded with the NAMPT inhibitor GMX1778, combined with a systemic anti-PD1 checkpoint blockade, resulted in higher T-cell recruitment and prolonged mice survival compared to monotherapy." (PMID 34068917, 2021). "NAMPT expression also correlates with high Nanog levels in patient-derived glioblastoma tumors, pointing to the role of NAMPT in maintaining the treatment-refractory component of glioblastoma." (PMID 33384409, 2021). "For example, inhibition of the NAD+ salvage pathway sensitized the glioblastoma-derived LN428 cell line to TMZ when the nicotinamide phosphoribosyl transferase (NAMPT) inhibitor FK866 was combined with the BER inhibitor methoxyamine (MX)." (PMID 33870196, 2021). "NAMPT is a potent oncogene and highly expressed in cancer cells and cancer tissues such as colon cancer, glioblastoma, etc." (PMID 31598701, 2019). "The downregulation of NAMPT in the IDH1R132H-overexpressing glioblastoma cell line U87-MG was also evident on the mRNA level." (PMID 31888244, 2019). "Chromosome 7 is usually disrupted in many cancers, here we detected the amplification of several genes already implicated in glioblastoma such as: EGFR, SEPT14, NAMPT, NRCAM, AAS and PTPRZ1." (PMID 29844869, 2018). "We found that NAMPT was highly overexpressed in glioblastoma tissue compared with healthy brain tissue." (PMID 29245920, 2017). "All these data strongly confirm that NAMPT levels correlates with the activation of the cancer stem cell–like phenotype in human glioblastoma tumors." (PMID 29245920, 2017). "According to the TCGA molecular classification of Glioblastoma, we found that NAMPT is particularly expressed in the Classical and Mesenchymal subtype." (PMID 29245920, 2017).